HCRT (hypocretin neuropeptide precursor)
Diseases named in the same sentence as HCRT in open-access papers (continued):
Sharing a sentence is not in itself a finding about the gene and the disease.
epilepsy (5 papers, 2015 to 2025). A brain disorder characterized by episodes of abnormally increased neuronal discharge resulting in transient episodes of sensory or motor neurological dysfunction, or psychic dysfunction. "In our hands, 4-PBA treatment rescued several disease-linked misfolded hCRT-1 mutants associated with intellectual disability and epilepsy." (PMID 36741049, 2022). "The chemical chaperone (and putative HSP70 modulator) 4-PBA, restored the activity of folding-deficient hCRT-1 mutants linked to severe intellectual disability and epilepsy in our recent studies." (PMID 36741049, 2022).
mood disorder (4 papers, 2016 to 2021). A cognitive disorder a disturbance in which the person's mood is hypothesized to be the main underlying feature. "We seized on the genes HCRT, KALRN, and HTR2A to substantiate the connection to mood disorders." (PMID 34987393, 2021).
Autoimmunity (3 papers, 2019 to 2022). The occurrence of an immune reaction against the organism's own cells or tissues. "The results of our study do not exclude a role of autoimmunity to HCRT, but identify with POMT1 another autoantigen in NT1." (PMID 33863907, 2021).
laryngeal carcinoma (2 papers, 2018). Carcinoma that arises from the laryngeal epithelium. "We also found significantly lower methylation of the HCRT gene in laryngeal cancers compared to hypopharyngeal cancers and oral cavity cancers (p = 0.016 and p = 0.025, respectively)." (PMID 29361757, 2018). "Moreover, to our knowledge, our study is the first to suggest that TAC1, HCRT, and GAL methylation is associated with worse DFS and that this may be a critical event in oral cancers, laryngeal cancers, and oropharyngeal cancers, respectively." (PMID 29682090, 2018).
amyloid (1 paper, 2022). "In support of a direct HCRT effect on Aβ homeostasis, there is evidence that HCRT has direct effects on both microglial phagocytosis of Aβ and on amyloid precursor protein (APP) processing in the hippocampus that support roles for HCRT in amyloid dyshomeostasis." (PMID 36275002, 2022).
behavior disorders (1 paper, 2021). "The detection of MIA associations with the previously enumerated transcript isoforms agrees with findings on behavior disorders, including reports that HCRT regulates sleep, feeding behavior, wakefulness, emotion, and stress response." (PMID 33834688, 2021).
kidney cancer (1 paper, 2017). Primary or metastatic malignant neoplasm involving the kidney. "Also, five parathyroid hormone-related proteins (PTHrPs) (PTHLH, PTH, HCRT, MC2R, and PTH2) are prominent for three kidney cancers (KICH, KIRC, and KIRP)." (PMID 28676692, 2017).
papilloma (1 paper, 2017). A benign epithelial neoplasm that projects above the surrounding epithelial surface and consists of villous or arborescent outgrowths of fibrovascular stroma. "Previous studies indicate that in vivo electroporation greatly enhances DNA delivery (44, –, 46), and therefore, the 4 SKH-1 mice with persistent papillomas were vaccinated three times biweekly with hCRT-mE6mE7mL2 DNA by in vivo electroporation." (PMID 28515303, 2017). "Therefore, we generated a DNA vaccine that expresses hCRT fused with MmuPV1 E6, E7, and L2 (amino acids [aa] 11 to 200) (hCRT-mE6mE7mL2) to assess whether the persistent papillomas in SKH-1 mice could be treated by vaccination." (PMID 28515303, 2017).
infection (5 papers, 2017 to 2024). The state of being infected such as from the introduction of a foreign agent such as serum, vaccine, antigenic substance or organism. "Thus, 10 SKH-1 mice that never developed warts after MmuPV1 infection were divided into two groups: 5 were treated three times biweekly with DNA vaccination with hCRT-mE6mE7mL2 and electroporation, and 5 received no treatment." (PMID 28515303, 2017).
neurodegenerative disease (5 papers, 2014 to 2025). A disorder of the central nervous system characterized by gradual and progressive loss of neural tissue and neurologic function. "The sleep disorder narcolepsy is now considered a neurodegenerative disease because there is a massive loss of neurons containing the neuropeptide hypocretin/orexin (HCRT)." (PMID 24736646, 2014).
HCRT also shares sentences with these, for which no sentence is quoted: depression (24 papers); hypersomnia (14); sleep disorder (14); Hypoglycemia (8); Coma (6); dementia (6); cancer (5); diabetes mellitus (5); Headache (5); Parkinson disease (5); Stroke (5); chronic obstructive pulmonary disease (4); hepatocellular carcinoma (4); Hypertension (4); Insulin resistance (4); memory impairment (4); narcolepsy type 2 (4); pancreatic cancer (4); Sleep apnea (4); tumor (4); colon carcinoma (3); experimental autoimmune encephalomyelitis (3); frontotemporal dementia (3); hippocampal atrophy (3); hypocretin deficiency (3); idiopathic hypersomnia (3); ischemic stroke (3); neuroblastoma (3); neurological disorders (3); alcohol dependence (2).
A further 100 diseases each share a sentence with HCRT in 2 papers or fewer.